NADK (NAD kinase)
Diseases named in the same sentence as NADK in open-access papers:
NADK is named in the same sentence as 31 diseases in open-access papers, as found by Europe PMC text mining. Sharing a sentence is not in itself a finding about the gene and the disease. The quoted sentences say what the papers report.
colorectal cancer (3 papers, 2021 to 2025). A primary or metastatic malignant neoplasm that affects the colon or rectum. "It is well known that the silencing of NADK impairs cancer growth in human colorectal cancer, but only one inhibitor has so far been described." (PMID 34880756, 2021). "Finally, we demonstrated that NFATc1 inhibitors suppress colorectal cancer (CRC) growth by targeting the NFATc1/NADK and NFATc1/MDM2 axis and synergize with oxaliplatin." (PMID 41203626, 2025). "Cytosolic NADK is overexpressed in several tumours, including colorectal cancer." (PMID 34880756, 2021). "Interestingly, an increase in IBD/IBS was also observed for CA13 (carbonic anhydrase XIII), protein associated with colorectal cancer (CRC), as well as SNAP23 (synaptosomal-associated protein 23) and NADK (NAD kinase) which are linked to insulin signalling and type 2 diabetes mellitus (T2DM)." (PMID 40481885, 2025).
lung carcinoma (3 papers, 2023 to 2025). "Conversely, mutations in NADK identified among cancer patients alter the tetramer conformation, resulting in NADK inactivation and increasing the sensitivity of lung cancer cells to chemotherapy." (PMID 40330153, 2025). "Analysing the mRNA levels of 56 paired lung cancer tissue and normal tissue showed that NADK expression was increased in tumor tissues compared with adjacent nontumor tissues." (PMID 37416767, 2023). "Western blot experiments showed that NADK protein levels were significantly increased in lung cancer tissues (8/9)." (PMID 37416767, 2023). "We first measured the mRNA levels of NADK in lung cancer cell lines and lung cancer tissues." (PMID 37416767, 2023). "The expression level of NADK in lung cancer cells was higher than that in normal cells." (PMID 37416767, 2023). "Therefore, it is of great importance to study the therapeutic effects of NADK inhibitors in lung cancer." (PMID 37416767, 2023). "Lung cancer cells with phosphorylated NADK show improved growth ability." (PMID 37416767, 2023). "It has been reported that phosphorylation of NADK by AKT (p-NADKS44/46) upregulates the enzymatic activity of NADK, and p-NADKS44/46 shows a stronger proliferation-promoting function in lung cancer cells than that of wild-type NADK19." (PMID 37416767, 2023). "Resistance to ferroptosis exists in lung cancer, but the role of NADK in regulating ferroptosis in lung cancer has not been reported yet." (PMID 38700533, 2024). "Immunohistochemistry (IHC) examination of lung cancer tissue arrays (containing 81 pairs of adjacent nontumor tissues and tumor tissues) revealed that the expression level of NADK protein was significantly increased in lung cancer tissues." (PMID 37416767, 2023).
breast carcinoma (2 papers, 2021 to 2024). "It has been reported that NADK-mediated NADPH increase is an important contributor to breast cancer metastasis." (PMID 38700533, 2024). "Akt has also been shown to affect NADPH production by directly phosphorylating NAD kinase (NADK) and in oncogenic PI3K breast cancer cell line T47D, Akt phosphorylation of NADK facilitated anchorage-independent cell growth." (PMID 34298660, 2021).
colon cancer (2 papers, 2025). "We investigated the correlation between NFATc1 and NADK in clinical colon cancer samples using data from the TCGA database." (PMID 41203626, 2025). "NADK inhibitors could represent clinically relevant drugs in cancer therapy, such as the lead compound thionicotinamide, an NADK inhibitor prodrug already assayed on human B-cell lymphoma and colon cancer xenograft mice." (PMID 39940737, 2025).
pancreatic cancer (2 papers, 2023 to 2025). "In addition, the NADK I90F mutation has been found to exhibit higher enzymatic activity in pancreatic cancer, and by altering tumor redox homeostasis, it regulates pancreatic cancer progression." (PMID 37416767, 2023). "In pancreatic cancer, PKC phosphorylated NADK, increased its activity, and promoted NADPH synthesis." (PMID 37416767, 2023).
pancreatic ductal adenocarcinoma (2 papers, 2023 to 2024). An infiltrating adenocarcinoma that arises from the epithelial cells of the pancreas. "However, it has been reported that in pancreatic ductal adenocarcinoma, KRAS mutations promote the phosphorylation of NADK by PKC, which increases NADK activity and promotes the synthesis of NADPH, promoting the progression of pancreatic cancer." (PMID 37416767, 2023). "Moreover, increased NADK activity is also involved in pancreatic ductal adenocarcinoma (PDAC)." (PMID 38700533, 2024).
COVID-19 (1 paper, 2022). A disease caused by infection with severe acute respiratory syndrome coronavirus 2. "In random forest models for COVID-19, CST5, DPP7, NADK, KYAT1 and TYMP showed the highest variable importance." (PMID 35967328, 2022). "After adjusting for confounding factors, CST5, NADK, SRPK2 and TGF-α were differentially detected in COVID-19 and non-COVID-19 patients." (PMID 35967328, 2022).
gastric cancer (1 paper, 2025). A primary or metastatic malignant neoplasm involving the stomach. "Consistently, in CRC HT29 and gastric cancer HGC-7901 cell lines, NFATc1 knockdown significantly reduced the transcriptional activity of NADK." (PMID 41203626, 2025).
glioblastoma (1 paper, 2019). The most malignant astrocytic tumor (WHO grade IV). "Indeed, we found, overall, higher levels of NAD+-synthesis enzymes NAMPT, NMRK1, and QPRT as well as NADK in primary glioblastomas compared to low-grade gliomas and astrocytes in our and publicly available data, indicating an overall increase in NAD+-biosynthesis in malignant cells." (PMID 31888244, 2019).
lung adenocarcinoma (1 paper, 2024). A carcinoma that arises from the lung and is characterized by the presence of malignant glandular epithelial cells. "Immunohistochemistry (IHC) was used to analyse the expression of NADK in 86 cases of lung adenocarcinoma(LUAD) and adjacent tissues, and a IHC score was assigned to each sample." (PMID 38700533, 2024). "To investigate the role of NADK in LUAD, we knocked down NADK expression in lung adenocarcinoma cell lines A549 and H1299 by transient transfection of siRNA or lentivirus- mediated deliver shRNA techniques." (PMID 38700533, 2024).
lymph node metastasis (1 paper, 2023). "Moreover, a higher positive rate of lymph node metastasis indicates a higher probability of expressing a higher level of NADK." (PMID 37416767, 2023). "Additionally, the lymph node metastasis rate was higher in patients with high NADK expression." (PMID 37416767, 2023). "In our study, NADK expression showed positive correlations with the TNM and AJCC stages of NSCLC patients, especially lymph node metastasis." (PMID 37416767, 2023).
neutropenia (1 paper, 2022). A decrease in the number of neutrophils found in the blood. "We also noticed a strong depletion of neutrophils in larvae infected with S. aureus/pSD1, while this neutropenia was more limited upon infection with NADK knockdown bacteria." (PMID 35723663, 2022). "NADK was necessary for successful S. aureus infection of zebrafish larvae, ultimately leading to neutropenia and death." (PMID 35723663, 2022).
ovarian carcinoma (1 paper, 2019). A malignant neoplasm originating from the surface ovarian epithelium. "To further validate the role of NADK in cancer treatment, we performed an in vivo assays by using another ovarian cancer cell line HEY, which has been listed in group III." (PMID 30741937, 2019).
ovarian tumor (1 paper, 2019). "Accordingly, the levels of NADP+ positively correlated with the levels of NADK in ovarian tumor cells." (PMID 30741937, 2019).
pneumonia (1 paper, 2017). An acute, acute and chronic, or chronic inflammation focally or diffusely affecting the lung parenchyma, caused by an infection in one or both of the lungs (by bacteria, viruses, fungi, or mycoplasma.). "In the set of domains that mainly contributed to separation of the pneumonia cluster from the hominis/spiroplasma cluster, a functional domain related to NAD kinase activity, needed for the production of NADP+, was found." (PMID 28224116, 2017).
cancer (17 papers, 2016 to 2025). A tumor composed of atypical neoplastic, often pleomorphic cells that invade other tissues. "Our findings partially unveil the structural basis for NADK regulation, offering insights into the cancer etiology of patients carrying NADK mutations." (PMID 40330153, 2025). "More importantly, cancer cells bear NADK mutations endowed of increase enzymatic activity, inducing higher production of NADPH and reduction of ROS, sustaining cancer cell viability." (PMID 34880756, 2021). "However, how human NADK activity is regulated, and how dysregulation or mutation of NADK is linked to human diseases, such as cancers, are still not fully understood." (PMID 40330153, 2025). "A methylation-deficient mutant, R45H, within the N-terminal region results in increased NADK activity and confers cancer chemotherapy resistance." (PMID 40330153, 2025). "Many cancers exhibit elevated NADK expression and demonstrate resistance to ferroptosis-inducing therapies." (PMID 41462596, 2025). "NADK has also been observed to play a role in physiology and pathophysiology of diseases, including cancers." (PMID 32111066, 2020). "They demonstrated that the combination treatment of NADPS with methotrexate displayed a synergic effect in metastatic colon cancer cell lines and proposed NAD kinase as a valid target for further inhibitor development for cancer treatment." (PMID 30909399, 2019). "Recently, two different strategies were used to restrain the growth of cancer cells by inhibiting NADK activity." (PMID 29662499, 2018). "Thionicotinamide adenine dinucleotide phosphate is also used as an inhibitor of NADK to accelerate the degradation of dihydrofolate reductase and thus to inhibit the growth of cancer cells." (PMID 29662499, 2018). "Inhibition of NADK activity with shRNA or thionicotinamide increased the ROS production in cancer cells which led to synergistic cell death." (PMID 29662499, 2018). "This study further affirmed NADK as a promising target for cancer treatment." (PMID 31752261, 2019). "NADP+ is generated from NAD+ by NADK, which is also a potential target for cancer chemotherapy." (PMID 30741937, 2019). "Interestingly, due to the essential roles in ROS homeostasis and cell survival under stress conditions, NADK has been considered as a drug target in anti-cancer medicine research." (PMID 29662499, 2018). "In addition, we show that depletion of wild-type NADK in PDAC cell lines attenuated cancer cell growth in vitro and in vivo." (PMID 26806015, 2016). "Thus, targeting NADK in cancer has been recognized as another potential anti-cancer target." (PMID 32111066, 2020). "Moreover, human NADK is also a therapeutic target for cancer." (PMID 31752261, 2019). "The authors identified an inhibitor of NAD kinase, thionicotinamide adenine dinucleotide phosphate (NADPS), which accelerated the degradation of DHFR and inhibited cancer cell growth." (PMID 30909399, 2019). "Benzamide riboside, a drug targeted to NADK, can reduce NADP and NADPH levels, and therefore treatment with this drug can lead to the process of DNA synthesis and growth of cancer cells being inhibited." (PMID 29662499, 2018). "Additionally, the CNV condition and expression level of ASF1A, CDKN2A, MAGOHB, NADK, SPOP, and ARC were remarkably correlated in most cancer types." (PMID 37497116, 2023). "In this study, NAD kinase was identified in increased urinary levels in PCa patients compared to ‘No Cancer’ samples." (PMID 35454901, 2022). "As mutant IDH requires NADPH to produce D-2HG, thus, a NADK inhibitor might be a novel therapeutic approach for treating mutant IDH cancer cells to decrease the NADPH pool which may not be sufficient to facilitate the production of the D-2HG oncometabolite." (PMID 32111066, 2020).
cancer (continued). "We further validate mutant NADK, whose expression provides gain-of-function enzymatic activity leading to a reduction in cellular reactive oxygen species and tumorigenesis, and show that depletion of wild-type NADK in PDAC cell lines attenuates cancer cell growth in vitro and in vivo." (PMID 26806015, 2016).
tumor (12 papers, 2014 to 2025). "Collectively, these findings indicate that NADK is highly expressed in LUAD, and elevated NADK expression is associated with poor tumor differentiation, lymph node metastasis as well as poor prognosis in LUAD patients." (PMID 38700533, 2024). "So, we utilized NIFE to inhibit NFATc1 and demonstrated that it exerts anti-tumor effects by suppressing both the NFATc1/NADK and NFATc1/MDM2 signaling pathways." (PMID 41203626, 2025). "It has been reported that NADK can regulate tumor cell proliferation and metastasis by modulating cellular metabolism." (PMID 38700533, 2024). "Compared with the control group, NADK overexpression led to larger tumor size, an increased tumor growth rate, and higher tumor weight." (PMID 37416767, 2023). "Next, to verify the function of NADK in promoting the tumor growth, we first subcutaneously inoculated LLC cells overexpressing NADK into C57/BL6 mice." (PMID 37416767, 2023). "Previous study has revealed that NADK knockdown or inhibition inhibited tumor proliferation.We found that the expression of NADK was increased in regorafenib-resistant cells." (PMID 38111012, 2023). "Although this mutation was present in only one tumor, further analysis in other pancreatic ductal adenocarcinoma (PDA) tumors indicated an increased expression of wild-type NADK." (PMID 31288436, 2019). "In contrast, ectopic expression of NADK markedly sensitized MDAH2774 tumor xenografts to olaparib treatment." (PMID 30741937, 2019). "Together, these data combined with the recognized importance of maintaining a redox state for PDAC tumour growth nominate NADK for additional target biology aimed at establishing its role as a novel target for drug development." (PMID 26806015, 2016). "Together, these data indicate that the I90F mutation in NADK provides GOF activity, leading to an increase in tumorigenesis and tumour growth by HPDE cells." (PMID 26806015, 2016). "Wild-type NADK exhibited very weak tumour-initiating activity (N=4/10), as three of the four NADKWT tumours remained growth-static or -regressed." (PMID 26806015, 2016). "Our primary screen revealed high enrichment for a mutant ORF encoding NADK (NADKI90F), which was identified by the ICGC13 to be mutated in a single tumour (PCSI0023_T)." (PMID 26806015, 2016). "NADK has emerged as a high-priority candidate with tumor metabolism-related characteristics." (PMID 41203626, 2025). "Here, our data further validated that NADK was overexpressed in LUAD tissues relative to adjacent non-cancerous tissues, and high NADK expression was associated with poor tumor differentiation, lymph node metastasis, and poor prognosis in LUAD patients." (PMID 38700533, 2024). "NADK expression positively correlated with lymph node metastasis and tumor stage in NSCLC patients." (PMID 37416767, 2023). "Moreover, patients with high NADK expression (pathological grade greater than grade II) exhibited a poor degree of tumor differentiation relative to those with low NADK expression (pathological grade less than or equal to grade II), and are more prone to lymph node metastasis." (PMID 38700533, 2024). "Therefore, we propose that NADK may be involved in tumor cell resistance to ferroptosis." (PMID 38700533, 2024). "For instance, activated AKT directly phosphorylates NAD kinase (NADK) to produce NADP+, facilitating tumor cell proliferation." (PMID 38263319, 2024). "NADK deletion in PDA cells led to increased ROS, inhibition of cell proliferation and tumor volume." (PMID 31288436, 2019).
bacterial infection (1 paper, 2022). "We demonstrated that NADK contributes to resistance to ROS produced by macrophages, neutralizing an important defense mechanism against bacterial infection." (PMID 35723663, 2022).
infection (1 paper, 2022). The state of being infected such as from the introduction of a foreign agent such as serum, vaccine, antigenic substance or organism. "We establish the first link between NADK activity and S. aureus pathogenic potential, as NADK inhibition led to an increased survival of the host in a zebrafish infection model." (PMID 35723663, 2022). "In this study, we used a genetic approach to modulate NADK activity and analyze S. aureus behavior in the infected host, in infected cells and in response to stresses mimicking those encountered during infection." (PMID 35723663, 2022). "Since both neutrophils and macrophages are key immune cells specialized in the destruction of microorganisms, we next investigated if, in addition to triggering neutrophil killing, NADK might support S. aureus survival during macrophages infection." (PMID 35723663, 2022). "We investigated whether NADK inhibition might influence S. aureus pathogenesis in a zebrafish infection model." (PMID 35723663, 2022). "Decreased fish mortality upon S. aureus/NADK sgRNA infection was also observed 48 and 72 hpi." (PMID 35723663, 2022). "The importance of microbial metabolic adaptation during infection and the unknown contribution of NADK to bacterial pathogenesis prompted us to investigate the role of NADK in Staphylococcus aureus pathogeny." (PMID 35723663, 2022). "In contrast, after 2 hr of infection the percentage of intracellular bacteria was significantly reduced upon ppnK knockdown, and the survival defect increased over time, indicating that bacteria were not able to survive inside macrophages without proper NADK activity." (PMID 35723663, 2022).
neurodegenerative disease (1 paper, 2025). A disorder of the central nervous system characterized by gradual and progressive loss of neural tissue and neurologic function. "Simultaneously, NADK activation may enhance the anti-aging effects of nutritional interventions such as NMN and improve their therapeutic efficacy in neurodegenerative disease management." (PMID 41462596, 2025).
NADK also shares sentences with these, for which no sentence is quoted: Diabetes (2 papers); Obesity (2); B-cell lymphoma (1); Birk-Landau-Perez syndrome (1); Constipation (1); glioma (1); kidney diseases (1); liver cancer (1); renal cell carcinoma (1); renal fibrosis (1); type 2 diabetes mellitus (1).